NR1D2 (nuclear receptor subfamily 1 group D member 2)
Description:
Transcriptional repressor which coordinates circadian rhythm and metabolic pathways in a heme-dependent manner. Integral component of the complex transcription machinery that governs circadian rhythmicity and forms a critical negative limb of the circadian clock by directly repressing the expression of core clock components BMAL1 and CLOCK. Also regulates genes involved in metabolic functions, including lipid metabolism and the inflammatory response. Acts as a receptor for heme which stimulates its interaction with the NCOR1/HDAC3 corepressor complex, enhancing transcriptional repression. Recognizes two classes of DNA response elements within the promoter of its target genes and can bind to DNA as either monomers or homodimers, depending on the nature of the response element. Binds as a monomer to a response element composed of the consensus half-site motif 5'-[A/G]GGTCA-3' preceded by an A/T-rich 5' sequence (RevRE), or as a homodimer to a direct repeat of the core motif spaced by two nuclegotides (RevDR-2). Acts as a potent competitive repressor of ROR alpha (RORA) function and also negatively regulates the expression of NR1D1. Regulates lipid and energy homeostasis in the skeletal muscle via repression of genes involved in lipid metabolism and myogenesis including: CD36, FABP3, FABP4, UCP3, SCD1 and MSTN. Regulates hepatic lipid metabolism via the repression of APOC3. Represses gene expression at a distance in macrophages by inhibiting the transcription of enhancer-derived RNAs (eRNAs). In addition to its activity as a repressor, can also act as a transcriptional activator. Acts as a transcriptional activator of the sterol regulatory element-binding protein 1 (SREBF1) and the inflammatory mediator interleukin-6 (IL6) in the skeletal muscle (By similarity). Plays a role in the regulation of circadian sleep/wake cycle; essential for maintaining wakefulness during the dark phase or active period (By similarity). Key regulator of skeletal muscle mitochondrial function; negatively regulates the skeletal muscle expression of core clock genes and genes involved in mitochondrial biogenesis, fatty acid beta-oxidation and lipid metabolism (By similarity). May play a role in the circadian control of neutrophilic inflammation in the lung (By similarity).
Synonyms: RVR; EAR-1R; BD73; HZF2; Hs.37288; REVERBB; REVERBbeta
Tractability: Small molecule: a structure with a bound ligand is known; it belongs to a druggable protein family. PROTAC: UniProt records ubiquitination sites on it; ubiquitination databases record sites on it; a small molecule that binds it is known.
Target class: Nuclear hormone receptor subfamily 1 group D; Transcription factor; Nuclear hormone receptor subfamily 1; Nuclear hormone receptor subfamily 1 group D member 2; Nuclear receptor
Gene: Protein-coding gene on chromosome 3 (23,945,286 to 23,980,637, forward strand). Ensembl gene ENSG00000174738.
Subcellular location: Nucleus; Cytoplasm
Subcellular location (Human Protein Atlas): Nucleoplasm
Pathways (Reactome):
Gene expression (Transcription): Nuclear Receptor transcription pathway
Gene Ontology:
Molecular function: protein binding; RNA polymerase II cis-regulatory region sequence-specific DNA binding; sequence-specific double-stranded DNA binding; DNA-binding transcription factor activity, RNA polymerase II-specific; nuclear receptor activity; cis-regulatory region sequence-specific DNA binding; DNA binding; DNA-binding transcription factor activity; DNA-binding transcription repressor activity, RNA polymerase II-specific; sequence-specific DNA binding; zinc ion binding
Biological process: negative regulation of DNA-templated transcription; cell differentiation; circadian behavior; energy homeostasis; hormone-mediated signaling pathway; intracellular receptor signaling pathway; lipid homeostasis; negative regulation of transcription by RNA polymerase II; positive regulation of DNA-templated transcription; positive regulation of transcription by RNA polymerase II; regulation of circadian rhythm; regulation of DNA-templated transcription; regulation of inflammatory response; regulation of lipid metabolic process; regulation of skeletal muscle cell differentiation; negative regulation of inflammatory response
Cellular component: nucleoplasm; nucleus; chromatin; cytoplasm
Genetic constraint (gnomAD): Loss-of-function variants: 22 observed, 44.73 expected, observed/expected ratio (o/e) 0.49, 90% interval 0.35 to 0.7. The upper end of that interval is the gene's LOEUF score, 0.7, which puts it in group 2 of 6, group 1 being the genes least tolerant of losing a copy. Missense variants: 629 observed, 687.56 expected, observed/expected ratio (o/e) 0.91, 90% interval 0.86 to 0.98. Synonymous variants: 250 observed, 227.22 expected, observed/expected ratio (o/e) 1.1, 90% interval 0.99 to 1.22.
Homologues: Orthologues: macaque NR1D2 (99% identical), chimpanzee NR1D2 (99% identical), dog NR1D2 (98% identical), pig NR1D2 (97% identical), guinea pig NR1D2 (96% identical), rabbit NR1D2 (96% identical), mouse Nr1d2 (91% identical), rat Nr1d2 (88% identical), tropical clawed frog nr1d2 (64% identical), zebrafish nr1d2b (59% identical), zebrafish nr1d2a (51% identical), Caenorhabditis elegans sex-1 (21% identical), and 184 more. Paralogues in human: NR1D1 (50% identical), RORA (25% identical), RORC (25% identical), PPARG (24% identical), RORB (24% identical), PPARA (23% identical), PPARD (23% identical), RARG (23% identical), RARB (22% identical), RARA (22% identical), THRB (21% identical), THRA (21% identical), and 6 more.
Diseases named in the same sentence as NR1D2 in open-access papers:
NR1D2 is named in the same sentence as 57 diseases in open-access papers, as found by Europe PMC text mining. Sharing a sentence is not in itself a finding about the gene and the disease. The quoted sentences say what the papers report.
glioblastoma (8 papers, 2020 to 2025). The most malignant astrocytic tumor (WHO grade IV). "In a cancer model of Drosophila, NR1D2 facilitates glioblastoma growth by maintaining the subpopulation of CSCs through the Hippo and Notch pathways." (PMID 40564218, 2025). "We have previously demonstrated that depleting NR1D2 impedes the cell mobility and viability of glioblastoma (GBM) - a highly aggressive and fatal brain tumor." (PMID 39516282, 2024). "We further validated these findings by demonstrating that depletion of NR1D2, the mammalian homolog of E75, inhibits the activation of Hippo and Notch target genes, impeding glioblastoma progression." (PMID 39516282, 2024). "NR1D2 regulates glioblastoma cell proliferation and motility and accelerates hepatocellular carcinoma progression by driving the epithelial-to-mesenchymal transition." (PMID 34440171, 2021). "REV-ERBβ (NR1D2) is highly expressed in glioblastoma, and is required for cell proliferation, migration and invasion." (PMID 32631383, 2020). "In glioblastoma CSCs, NR1D2 regulates proliferation through the AXL/PI3/Akt signalling pathways." (PMID 40564218, 2025). "A recent study reported that NR1D2 promotes the proliferation and mobility of glioblastoma cells." (PMID 39273313, 2024). "In that study, AXL was identified as a new transcriptional target of NR1D2: the regulatory effect of NR1D2 on the PI3K/AKT axis promotes the proliferation, migration, and invasion of glioblastoma cells." (PMID 39273313, 2024).
Obesity (7 papers, 2020 to 2022). Accumulation of substantial excess body fat. "Obesity resulted in overall disruption of core clock genes (i.e., Bmal1, Clock, Rev-erbα/Nr1d1, Rev-erbβ/Nr1d2, Per1, Per2, Cry1, Cry2, Dbp and Rorα) in WAT." (PMID 35198059, 2022). "SR9009, previously reported as a small molecule ligand for NR1D1 and NR1D2, had an important role in feedback regulation of the circadian oscillator and reversing obesity." (PMID 34587364, 2021). "Furthermore, mice with diet-induced obesity reduced fat mass and improved dyslipidemia and hyperglycemia after treatment of NR1D2 agonist." (PMID 32579418, 2020). "Similarly, genes encoding circadian clock regulators (Dbp, Nr1d1 and Nr1d2), KLF transcription factors (Klf2 and Klf6) and cell signaling molecules (Rhob and Shank3) were also upregulated in sustained obesity (cohort 2) but not in the reversion group (cohort 3)." (PMID 36400935, 2022).
glioma (5 papers, 2021 to 2025). A benign or malignant brain and spinal cord tumor that arises from glial cells (astrocytes, oligodendrocytes, ependymal cells). "An elevated level of NR1D2 (REV-ERBβ) expression was found to correlate positively with glioma grades." (PMID 40495887, 2025). "Results from this laboratory suggested that NR1D2 is involved in the migration and invasion of glioma cells through the receptor tyrosine kinase AXL." (PMID 34361055, 2021). "The differential expression of CCGs in glioma grading confirmed that cluster I genes (ARNRL, NPAS2, and TIMELESS) and CRY1, with cluster II genes (CRY2, DBP, NR1D1, NR1D2, PER2, PER3, and RORA) showed significantly opposite expression trends in brain tissues." (PMID 35832846, 2022). "Two genes that play important roles in circadian clock regulation, casein kinase-1 epsilon (CK-1ε) and the nuclear receptor NR1D2, were found to regulate GBM cell survival and were proposed as targets for glioma treatment." (PMID 34371781, 2021). "Besides, the expression of eight CCGs (CRY2, DBP, NR1D1, NR1D2, PER2, PER3, RORA, and TIMELESS) was negatively regulated by methylation and positively regulated by CNV in glioma, which is consisting with previous studies that DNA methylation and CNV can promote abnormal gene expression." (PMID 35832846, 2022).
atherosclerosis (4 papers, 2009 to 2020). A disease characterized by the build-up of fatty material and calcium deposition in the arterial wall resulting in partial or complete occlusion of the arterial lumen. "Nr1d2 also represses the expression of hepatic Apoc3 mRNA, a risk factor for atherosclerosis, and hepatic Insig1 overexpression reduces lipogenesis via decreased expression of Srebp1c mRNA and its target enzymes." (PMID 30423963, 2018). "These researches demonstrated that REV-ERB (including NR1D1 and NR1D2) played an important role in atherosclerosis." (PMID 32328084, 2020). "Some of the RORα-modulated genes are involved in physiological functions such as lipid metabolism (LPA, NR1D2, ADIPOQ also known as adiponectin) and inflammation (ADIPOQ, PLG), but also in related cardiovascular diseases such as atherosclerosis." (PMID 21818335, 2011).
breast carcinoma (4 papers, 2015 to 2021). "However, recently it has been shown that REV-ERBβ (NR1D2) is also expressed in breast cancer cell lines and that its expression not correlated with HER2 or ER expression." (PMID 26300846, 2015).
diabetes (4 papers, 2009 to 2026). "METHODS: The variants present in the exons and adjacent intronic regions of the NR1D2 gene in patients with MODY were subjected to comparative analysis with those observed in healthy individuals and patients with type 2 diabetes mellitus." (PMID 41649749, 2026). "A list of 15 known clock genes from the primary (Arntl, Clock, Npas2, Per1, Per2, Per3, Cry1, Cry2), secondary (Nrd1d1, Nr1d2, Rora, Rorb, Rorc), and accessory TTFL loops (Nfil3, Dbp) were selected to investigate the effect of diabetes on their rhythmic expression." (PMID 38039846, 2024).
hepatocellular carcinoma (4 papers, 2011 to 2025). A malignant tumor that arises from hepatocytes. "NR1D2 deficiency has been reported to inhibit the proliferation of hepatocellular carcinoma and glioblastoma cancer cells, indicating that NR1D2 has oncogenic potential." (PMID 37524704, 2023). "The nuclear receptor NR1D2 was delayed almost 8h compared to is homolog NR1D1, which is consistent with similar observations in live cell imaging of hepatocellular carcinomas in mouse liver (K. Padmanabhan, personal communication)." (PMID 40424435, 2025). "We thus identified SPARC, PLG, G6PC, NR1D2 and AGRP as RORα targets in hepatoma cells." (PMID 21818335, 2011).
colitis (3 papers, 2022 to 2026). Inflammation of the colon. "Several nuclear receptors were specifically downregulated in males (Vdr, Lrh1/Nr5a2, Mr/Nr3c2, Rev-erbβ/Nr1d2, Car/Nr1i3, Esrrg, Lxrα/Nr1h3) and have indeed been demonstrated to regulate key protective functions relating to colitis or CRC." (PMID 36142324, 2022).
lung carcinoma (3 papers, 2018 to 2024). "This includes genes involved in cancer progression such as Kif26a, Acer2, Serpine1, Nr1d2, Efnb2 as well as Chst11, which have all previously been shown to be deregulated in various forms of cancer, including lung cancer." (PMID 39273313, 2024). "However, as the role of NR1D2 in lung cancer is not known to date, we cannot exclude the possibility that NR1D2 acts as a tumor suppressor in lung cancer, similar to NR1D1." (PMID 37524704, 2023).
Anxiety (2 papers, 2020 to 2022). Intense feelings of nervousness, tension, or panic often arise in response to interpersonal stresses. "We found that individuals with advanced circadian phase and evening preferences (low MEQ scores) are six times more likely to report anxiety (PER3: OR 5.88 (1.22–28.40), p = 0.027; Nr1d2: OR 6.50 (0.77–58.48), p = 0.085)." (PMID 35365695, 2022).
arterial hypertension (2 papers, 2021 to 2022). "The nuclear receptor NR1D2 promotes expression of the inflammatory mediator, interleukin 6, a pathway that has been described to be involved in trophoblast hypoxia, arterial hypertension, placental inflammation, and autophagy in gestational diabetes mellitus." (PMID 36284122, 2022).
asthma (2 papers, 2016 to 2017). "NR1D2 and PER3 have been associated with asthma in mice through bioinformatics analysis of genes and pathways." (PMID 28886691, 2017).
brain tumor (2 papers, 2024). "Genes including CRY2, NR1D2, and PER3, were found to have a positive correlation with high overall survival (OS) and disease-free survival (DFS) in brain tumor patients." (PMID 39043735, 2024).
colorectal cancer (2 papers, 2022 to 2025). A primary or metastatic malignant neoplasm that affects the colon or rectum. "In our present study, colorectal cancer likely enters the muscle from blood exosomes and regulates skeletal muscle atrophy through miRNA‒mRNA regulatory network mechanisms, and celastrol treats muscle through NR1D2 in the miRNA‒mRNA regulatory network." (PMID 36419834, 2022).
congenital heart disease (2 papers, 2016 to 2023). A heart disease that is present at birth. "We also identified that downregulation of NR1D2, a gene involved in congenital heart disease, was a feature of aging-related transcriptional network in aged macrophage, fibroblast and pericyte." (PMID 37084237, 2023). "De novo mutations in NR1D2 or any gene in the cardiac malformation module were absent from 59 control trios without congenital heart disease." (PMID 27058611, 2016).
depression (2 papers, 2009 to 2015). "Intriguingly, Bhlhe40, Dbp and Nr1d2 are among the top-ranked genes that are rhythmically expressed in the human brain, and individuals with major depressive disorder appear to have lost the alignment between Bhlhe40 and Per2 expression timetables in six brain regions, e.g. in the amygdala." (PMID 25820768, 2015). "By stimulatory binding at D-box promoter sites, TEF may promote transcription of NR1D1, NR1D2, and the PER genes, actions which might be supposed to stimulate mania or counter depression." (PMID 19166596, 2009).
osteosarcoma (2 papers, 2022 to 2024). A usually aggressive malignant bone-forming mesenchymal neoplasm, predominantly affecting adolescents and young adults. "Therefore, this study aimed to identify the redundant and distinct roles of each isoform in controlling its target genes by comparing the transcriptome profiles of a panel of mutant U2OS human osteosarcoma cells in which either NR1D1 or NR1D2 was ablated." (PMID 38255844, 2024). "In “Myeloid”, differentially expressed NRs such as NR4A2, NR4A1, NR3C1, RXRA, NR1D2, PPARD, and RARA were identified among metastasis, primary, and recurrent osteosarcoma tissues." (PMID 35965537, 2022).
septic shock (2 papers, 2021 to 2025). Shock caused by infection; frequently caused by gram negative bacteria, although some cases have been caused by other bacteria, viruses, fungi, and protozoa; characterized by fever, chills, tachycardia, tachypnea, and hypotension. "In a study of circadian rhythms in septic shock, CRY2 and NR1D2 had the highest rhythmicity in patients." (PMID 40362233, 2025). "In summary, the positive regulators of the transcriptional–translation feedback loop (CLOCK and ARNTL) were the least rhythmic, while negative regulators (NR1D1, NR1D2, CRY2) were the most rhythmic in septic shock patients." (PMID 33900485, 2021). "While CRY1, NR1D1, NR1D2, DBP, PER2 were suppressed in septic shock patients, CRY2, surprisingly was significantly upregulated compared to healthy young men." (PMID 33900485, 2021). "In addition, the expression of the clock genes CRY1, NR1D1, NR1D2, DBP, and PER2 were suppressed in septic shock patients, whereas CRY2 was significantly upregulated compared to healthy young men." (PMID 33900485, 2021).
steatosis (2 papers, 2020). Increased lipid within the cytoplasm of cells. "Bmal1 is thought to induce lipogenesis, whereas Nr1d2 controls lipid metabolism and its reduced expression promotes lipogenesis and steatosis." (PMID 33287957, 2020).
cataract (1 paper, 2025). Partial or complete opacity of the crystalline lens of one or both eyes that decreases visual acuity and eventually results in blindness. "A DT model trained on the in vivo dataset (GSE230320), using the genes PLAGL2, CMTM7, NR1D2, and PCYT1B, not only accurately predicted cataracts in the other in vivo dataset but also demonstrated good predictive performance in two separate ex vivo datasets." (PMID 40027191, 2025). "NR1D2 and PLAGL2 had a minor negative influence on predicting “no cataracts”." (PMID 40027191, 2025).
cryptorchidism (1 paper, 2016). The failure of one or both testes of a male fetus to descend from the abdomen into the scrotum during the late part of pregnancy. "Thus, the aberrant downregulation of NR1D2 in patients with MA and cryptorchidism may be caused by the aberrant increase in miR-210." (PMID 27562222, 2016). "Herein, we report that NR1D2 was localized in spermatogonia and spermatocytes and was downregulated in MA patients and those with cryptorchidism." (PMID 27562222, 2016). "We demonstrated that miR-210 acts as an upstream regulator of NR1D2 function in human cryptorchidism." (PMID 27562222, 2016). "Furthermore, NR1D2 was aberrantly expressed in patients with MA or cryptorchidism in this study." (PMID 27562222, 2016). "To investigate the potential role of miR-210 in spermatogenesis and cryptorchidism, we studied the correlation between miR-210 and NR1D2 in the testicular embryonic carcinoma cell line NTERA-2 (NT-2) and explored potential targets of miR-210 that may participate in testis development." (PMID 27562222, 2016).
Duchenne muscular dystrophy (1 paper, 2022). Duchenne muscular dystrophy (DMD) is a neuromuscular disease characterized by rapidly progressive muscle weakness and wasting due to degeneration of skeletal, smooth and cardiac muscle. "There is an association between NR1D2 clock gene expression and mitochondrial quality control, while impaired oxidative capacity and mitochondrial function contribute to Duchenne muscular dystrophy." (PMID 36419834, 2022). "In the previous literature, NR1D2 was shown to regulate mitochondrial function by regulating the circadian rhythm, and impaired mitochondrial function leads to Duchenne muscular dystrophy." (PMID 36419834, 2022).